BRAF (B-Raf proto-oncogene, serine/threonine kinase)
Diseases named in the same sentence as BRAF in open-access papers (continued):
Sharing a sentence is not in itself a finding about the gene and the disease.
melanoma (continued). "To assess the effect of BRAF and ALK inhibition in vivo, we tested vemurafenib, ceritinib and the combination of both in mice harbouring A375-X1-induced melanoma tumours." (PMID 30290811, 2018). "Five patients (two BRAF V600E, one BRAF V600K, two NRAS Q61R) of 29 (17%) were found through clinical examination or imaging to have recurrent melanoma during the study period." (PMID 30113761, 2018). "Promising new therapies have emerged for BRAF‐mutant melanoma patients, but NRAS‐mutant (NRASMut) melanoma, like other RAS‐driven tumors, continues to have poor prognosis and limited therapeutic options." (PMID 29650805, 2018). "Functionally, dabrafenib led to a growth arrest in the BRAF‐ and RAS‐mutant melanoma cell lines, with a G1‐phase cell cycle arrest noted (~ 10% in WM1366 cells)." (PMID 29112787, 2018). "Specific inhibitors that target activated BRAF as well as the downstream MAPK/ERK signaling pathway have been developed, which dramatically reduce the growth of melanoma cells in patients." (PMID 30349559, 2018). "We identify SIRT6 as a regulator of resistance to the clinically relevant BRAF inhibitor (BRAFi), dabrafenib, or combination dabrafenib + trametinib (MEK inhibitor, MEKi) in BRAFV600E melanoma." (PMID 30143629, 2018). "Despite advancements in targeted therapies (BRAF inhibitors) or immunotherapies (anti-CTLA-4 or anti-PD1), most patients with melanoma will need additional treatment." (PMID 29743521, 2018). "Targeted inhibitors such as vemurafenib (BRAF inhibitors, BRAFi), trametinib (MEK inhibitor, MEKi) and the combination of BRAFi+MEKi have been approved by the FDA for advanced melanoma patients carrying the V600E residue of the BRAF protein." (PMID 30400954, 2018). "These mixed results indicate that AMPK-associated ERK deactivation in melanoma could be cell and stressor specific, or there are still several unidentified negative feedback loops that are operating between BRAF, MAPK and LKB1/AMPK pathways as suggested recently." (PMID 30651927, 2018). "In melanoma, MHC class I internalization induced by BRAF V600E has also been described, suggesting another potential mechanism underlying the enhanced tumor visibility resulting from BRAF inhibitor therapy." (PMID 29780391, 2018). "The effect of Ole on the cell viability was assessed on BRAF mutant (V600E) A375, WM266-4, and M21 melanoma cells following incubation for 72 h with an Ole concentration, ranging from 50 to 800 μM (corresponding to ≈25–400 μg/mL), using the MTT assay protocol." (PMID 30544808, 2018). "Further exploration of this topic will include multivariate survival analysis to determine if Cks1 is an independent prognostic variable and to evaluate whether Cks1 expression segregates with the presence or absence of specific gene mutations involved in melanoma such as BRAF and NRAS." (PMID 29423113, 2018). "To confirm these findings, we performed IGFBP2 immunohistochemistry (IHC) on treatment-naive tumor biopsies from 34 melanoma patients (21 BRAFV600E/K and 13 non-BRAF mutant tissues)." (PMID 30143629, 2018). "Studies using the biguanides metformin and phenformin, both indirect AMPK activators, showed minimal effects on ERK dephosphorylation in both BRAF wild type and BRAFV600E mutant, as well as NRAS mutant melanomas." (PMID 30651927, 2018). "Yet, for instance, treatment with PLX4032, a BRAF inhibitor, leads to PFS of 7 months in patients with hyper-activated BRAF melanomas." (PMID 29946532, 2018). "Based on these findings, clinical trials evaluating combinations of PD-1 blockade with BRAF inhibitors such as vemurafenib (NCT01656642), and with MEK inhibitors such as trametinib (NCT02224781) are now underway for melanoma." (PMID 29482595, 2018). "In conclusion, all these results demonstrated that glucose-derived glutamate contributes to increase the antioxidant defense in BRAFi-resistant melanoma cells in an NRF2-dependent manner, contributing to the survival to anti-BRAF therapy." (PMID 29487283, 2018).
melanoma (continued). "To identify any potential cooperation between the common oncogenic alterations with DOT1L mutation in melanoma development, we first analyzed the relationship between BRaf/NRas status and DOT1L status in the TCGA melanoma cohort." (PMID 29343685, 2018). "Further supporting a pro-oncogenic role in melanoma, LOXL3 favors tumor growth in vivo and cooperates with oncogenic BRAF in melanocyte transformation." (PMID 29229995, 2018). "Despite promising initial responses obtained with BRAF and MEK kinase inhibitors, resistance to treatment develops within months in virtually all melanoma patients." (PMID 30290811, 2018). "siRNA‐mediated knockdown of NEK9 using siRNA pools from two manufacturers (siNEK9#1 and #2) reduced the growth of both BRAF‐mutant (1205Lu) and NRAS‐mutant (WM1366, IPC‐298, and M245) melanoma cell lines." (PMID 29112787, 2018). "BRAF and MEK are protein kinases of the MAPK-ERK pathway, which in solid tumors such as melanoma enable proliferation and cell survival." (PMID 30233579, 2018). "On these bases, in the present study functional experiments were performed using melanoma cell models to confirm the correlation between MMP-9 expression and MAPK pathway modulation during the treatment with BRAF inhibitors." (PMID 30154717, 2018). "The practical relevance of the role of RIP1 in protecting melanoma cells from BRAF/MEK inhibitors was shown by studies in melanoma cells grown in 3D cultures, and more importantly, in paired fresh melanoma isolates before and after treatment with vemurafenib." (PMID 29880840, 2018). "Dabrafenib, a BRAF inhibitor and Trametinib, a MEK inhibitor are two molecularly targeted agents recently approved for treatment of advanced, unresectable melanomas." (PMID 30255823, 2018). "We reviewed cell line response data and confirmed that both oncogenic BRAF and NRAS predict sensitivity to MEK inhibition in melanoma." (PMID 30237495, 2018). "However, it is not known if leflunomide affects melanoma cells that do not harbor BRAF mutations and details of how leflunomide exerts its anti-melanoma effects are currently unknown." (PMID 29423085, 2018). "This mutation leads to a conformational change resulting in constitutive activation of BRAF, and consequently of the MEK/ERK MAPK pathway, promoting survival and proliferation of melanoma cells." (PMID 30651927, 2018). "The reduction of H3K4me3 and H3K9ac levels at mutant TERT promoters was similarly observed in BRAF-mutant, TERT (−146C > T) or TERT (−124C > T) melanoma cell lines, UACC257, A375, WM793, and Malme-3M, following si-BRAF treatment." (PMID 29541423, 2018). "Then we examined BRaf and NRas status in DOT1L-null mouse melanomas and found that BRaf (V637, homolog to human BRaf V600) mutations are frequently observed in melanomas from Dot1l-null transgenic mice (n = 4/7)." (PMID 29343685, 2018). "We next carried out experiments to evaluate the effects of E2F1 blocking in combination with BRAF inhibitor, PLX4032, in BRAF inhibitor-resistant melanoma cells." (PMID 29743521, 2018). "For melanoma there are five significant prognostic factors: age, KPS, extracranial metastases, number of BMs, and BRAF status." (PMID 29881714, 2018). "On this ground, we investigated the consequences of targeting BRAF and MEK, alone or in combination, in 3D and 2D in vitro models of melanoma." (PMID 30558661, 2018). "Activation of the Raf family kinases BRAF and CRAF is important for the pathogenesis of malignant melanoma." (PMID 29481571, 2018). "In melanoma, somatic deletions of tumor suppressors (e.g., PTEN) and duplications of oncogenes (e.g., BRAF) are known to have high incidence rates." (PMID 30477554, 2018). "This is particularly true for BRAF(V600) mutant disease and to a lesser extent for KIT mutant melanoma." (PMID 30405888, 2018). "Consistently, inhibition of SCD1 elicits lethal effects and override the intrinsic resistance to BRAF and MEK inhibitors that characterizes melanoma CSCs." (PMID 30558661, 2018).
melanoma (continued). "BRAF and NRAS both take part in the mitogen-activate protein kinase (MAPK) pathway which significantly contributes towards melanoma development." (PMID 29492238, 2018). "Targeted therapies as BRAF and MEK inhibitor combination have been approved as first-line treatment for BRAF-mutant melanoma." (PMID 29487283, 2018). "CRAF also co-immunoprecipitates with BRAF, implying that there is a triad of interactions between BRAF, CRAF, and HSP90 in human melanoma cells." (PMID 29481571, 2018). "Although BRAF-mutant drug-sensitive melanomas show increased apoptosis in response to BRAF or BRAF/MEK inhibition in vitro and in vivo, a sufficient number of cells frequently remains to allow the outgrowth of resistant melanomas at their original site." (PMID 30237393, 2018). "The first selective BRAF inhibitor approved by FDA and EMA in 2011 for the treatment of patients with metastatic or unresectable melanoma was vemurafenib, followed by dabrafenib which was approved by FDA and EMA in 2013." (PMID 30693134, 2018). "We next tested the performance of Calabrese in another cell line, MelJuSo, a BRAF-wildtype, NRAS-mutant melanoma line engineered to express dCas9-VP64." (PMID 30575746, 2018). "We also found that there was network rewiring in a small number of a priori created modules in both BRAF+ vs. BRAF− and BRAFV600E+ vs. BRAF−- melanoma cohorts." (PMID 30042785, 2018). "For example, in a melanoma PDX model introducing vemurafenib resistance, the resistant tumors showed dependency on BRAF signaling due to the elevated BRAF (V600E) expression." (PMID 30089794, 2018). "To check if miR-195 also sensitizes melanoma cells to BRAF inhibitor (vemurafenib, PLX4032), we transfected UACC-62 melanoma cells with miR-195 (25 nM) and treated with 1 μM and 10 μM PLX-4032 for 48 h." (PMID 29126391, 2017). "We show that BRAF expression is required for ERK activation and nevi development, demonstrating a critical role in the early stages of NRAS-driven melanoma." (PMID 28497782, 2017). "Furthermore, the effectiveness of trametinib and everolimus co-targeting against multiple distinct BRAF-fusions to in our study suggests that such strategies may offer synergistic targeting opportunities in other tumor subtypes, including melanoma where BRAF-fusions have begun to be characterized." (PMID 29156677, 2017). "In addition, the most commonly used murine melanoma model (B16) does not harbor a BRAF mutation." (PMID 28060736, 2017). "PI3K activation has been shown to overcome BRAF V600E-induced senescence in melanoma, and PI3K signaling was found to be enhanced in BRAFi-resistant melanomas." (PMID 28002790, 2017). "To dissect the underlying molecular mechanisms of adapted reactivation of the RTK/MAPK signaling in response to BRAF and combined BRAF/MEK inhibition, we conducted transcriptome gene profiling in vemurafenib-treated melanoma cells." (PMID 29050198, 2017). "Specifically, we explored the role of non-invasive imaging with PAI and MRI in detecting melanoma cell functional differentiation following treatment with the prototype Hsp90 inhibitor 17-AAG and the clinically relevant BRAF inhibitor vemurafenib." (PMID 28811486, 2017). "In summary, we have shown in this study that treatment with BRAF/MEK inhibitors upregulates CD47 expression through NRF-1, and that this is mediated by reactivation of ERK in melanoma cells." (PMID 29050218, 2017). "The limited duration of the response obtained with BRAF and MEK inhibition in BRAFV600 melanoma and the impressive durability but the relatively low response rate obtained with the block of the immune checkpoint molecules proved to be surprising." (PMID 28231855, 2017).
melanoma (continued). "Deletion of NRAS was also a rare event and was observed in 9.4% (3/32) of BRAF/NRAS WT and 3.3% (1/30) of HET melanomas." (PMID 28668077, 2017). "With this in mind, and to improve our understanding of the complexity of MITF‐high melanomas in the context of MAPK inhibitor resistance, we set out to analyse the dynamics of individual MITF‐expressing subpopulations during treatment with BRAF inhibitor." (PMID 28606996, 2017). "Similar enhanced anti-tumor combination activity was observed in a BRAF mutant (A375.X1) and NRAS mutant (IPC-298) melanoma model, suggesting the potential for application of this combination strategy in other MAPK-dysregulated settings." (PMID 28982154, 2017). "Recently, the potential of intermittent dosing schedules of BRAF and MEK inhibitors to extend disease control in BRAF mutant melanoma has been explored." (PMID 29100459, 2017). "In melanoma, for example, AKT signalling is an important resistant mechanism in BRAF positive cancer cells." (PMID 28854272, 2017). "BRAF and MEK inhibition in BRAFV600E melanoma patients found a small increase in median progression free survival but failed after a short time." (PMID 28094001, 2017). "Several studies have demonstrated that inhibition of MAPK pathway by BRAF and MEK inhibitors leads to increased expression of melanocyte differentiation antigens in both melanoma cell lines and clinical tumor samples from melanoma patients." (PMID 29156850, 2017). "A combination of BRAF and MEK inhibition further improves time to progression and overall survival in patients with metastatic melanomas when compared with single‐agent BRAF inhibition." (PMID 27974353, 2017). "Oncogenic activation of BRAF signaling in melanoma upregulates MCL-1 expression and contributes to increased resistance to BRAF/MEK inhibitors and overall tumor progression and survival." (PMID 27086916, 2017). "Using tamoxifen-controlled Raf gene recombination, we were also able to analyse the respective contribution of BRAF and CRAF in melanoma growth and maintenance." (PMID 28497782, 2017). "As up to 50% of BRAF mutant human melanomas express high levels of RhoJ, these studies nominate the RhoJ-BAD signaling network as a therapeutic vulnerability for fledgling BRAF mutant human tumors." (PMID 28753606, 2017). "Several Bcl2 proteins are downstream of commonly activated RAS/BRAF/MAPK and PI3K/Akt signaling pathways which play an important role in tumor initiation and maintenance of melanoma specific CSCs compartment." (PMID 28137308, 2017). "The co-occurrence of BRAF and EZH2 hyperactivation as illustrated in the precision medicine case in melanoma presented above opens new possibilities for targeted treatment." (PMID 28265786, 2017). "Given the high prevalence of the TERT promoter mutations C228T and C250T in cutaneous melanoma, their addition to existing tests for detection of mutant BRAF and NRAS will allow monitoring of most melanoma patients using ddPCR." (PMID 29108273, 2017). "It has been demonstrated in melanoma and lung cancer cells that MEK activated by CRAF is less sensitive to MEK inhibitors than, when the activation is via BRAF V600E." (PMID 28829399, 2017). "Treatment with BRAF/MEK inhibitors upregulated CD47 in cultured melanoma cells and fresh melanoma isolates." (PMID 29050218, 2017). "This could be important because the metastatic form of melanoma remains incurable by current therapies, despite a significant progress over the last years in the development of targeted therapeutics such as vemurafenib (PLX4032) or dabrafenib, small molecule inhibitors of mutated BRAF kinase." (PMID 28973015, 2017). "MLN2480 inhibited MAPK pathway signaling in preclinical BRAF and RAS mutant melanoma and colorectal carcinoma models." (PMID 28002790, 2017). "Unfortunately, drug resistance to BRAF or MEK inhibitors often develops within the first year of treatment and is accompanied by disease progression in many melanoma patients." (PMID 29209327, 2017).
melanoma (continued). "For example, the knowledge of the BRAF driving oncogenic lesion has guided the advent of BRAF and MEK inhibitors, effective in more than 50% of the treated melanoma patients." (PMID 29112174, 2017). "We tested the potential effect of BRAF inhibitors on the expression of CD47 in melanoma cells by treating Mel-CV and MM200 cells (BRAFV600E) with the BRAF inhibitor vemurafenib for various periods." (PMID 29050218, 2017). "Moreover, Trametinib has recently been approved for the treatment of adult BRAF-mutated melanoma, while different clinical trials with Selumetinib and MEK162 show promising results in adult patients with RAS/RAF mutation positive melanoma and non-small-cell lung cancer." (PMID 27588400, 2017). "In this study, we investigated the effect of HDACi treatment alone and in combination with the BRAF inhibitor, vemurafenib, on PMCA expression and on Ca2+ clearance in both BRAF-mutant and BRAF wild-type melanoma cell lines." (PMID 28596940, 2017). "Given the significantly better survival outcomes, the combined BRAF and MEK inhibition will become the mainstay therapy for BRAF V600-mutant melanoma." (PMID 28416755, 2017). "Combination therapy targeting both BRAF and MEK has also been reported to be well tolerated and to result in significant progression-free survival in melanoma." (PMID 28094001, 2017). "In summary, these findings support the clinical evaluation of MET-directed targeted therapy to circumvent resistance to BRAF and MEK inhibitors in BRAFV600E mutant melanoma." (PMID 28147313, 2017). "Similarly, the impact of a genetic alteration and response to treatment may be different in different tumors, for example, BRAF V600E mutation predicts response to single‐agent vemurafenib in melanoma but not in colorectal cancer." (PMID 28028924, 2017). "BRAF activation and MAPK signaling has been shown to drive tumor-specific methylation programs in colon cancer and possibly melanoma." (PMID 28396701, 2017). "As BAG3 protein is involved in sustaining BRAF levels and ERK phosphorylation in A375 melanoma cells, we sought to verify if BAG3 silencing can affect the response of those cells to prolonged Vemurafenib treatment." (PMID 29113311, 2017). "This mutation leads to a conformational change, resulting in constitutive activation of BRAF, and consequently of the MAPK/ERK pathway, promoting survival and proliferation of melanoma cells." (PMID 29100459, 2017). "In this study we observed a dominant role for the HGF/MET axis in mediating resistance to BRAF and MEK inhibitors in models of BRAFV600E and NRAS mutant melanoma." (PMID 28147313, 2017). "Clinical and pathological properties partly reflect the identified (BRAF, RAS, NF1, triple wild type) genomic subtypes of melanoma, but from both clinical and genetic perspective the groups still are heterogeneous." (PMID 28445515, 2017). "Initial reports documenting HGF-mediated resistance to BRAF inhibition in BRAF mutant melanoma identified correlations between HGF expression levels and patient response to BRAF and/or MEK inhibitor therapy." (PMID 28147313, 2017). "This low response rate is due in part to differential expression/activation of EGFR in colorectal cancer compared to melanoma, ultimately leading to MAPK pathway activation and thereby circumventing BRAF inhibition." (PMID 27999210, 2017). "The development of several new systemic treatment options including, BRAF and MEK as well as CTLA-4 and PD-1 targeting immune checkpoint inhibitors have revolutionized the daily practice of melanoma treatment." (PMID 28374234, 2017). "In this study, we found that the EPE peptide significantly reduced the viability of not only BRAF, but also several NRAS and NF1 mutant melanomas." (PMID 29180761, 2017). "We treated the three melanoma cell lines (MEWO, A2058, and A375) with HDAC and BRAF inhibitors alone and in combination for 48 h and tested their viability." (PMID 28596940, 2017).